ANKRD29 (ankyrin repeat domain 29)
Synonyms: FLJ25053
Tractability: PROTAC: ubiquitination databases record sites on it.
Gene: Protein-coding gene on chromosome 18 (23,598,926 to 23,663,088, reverse strand). Ensembl gene ENSG00000154065.
Subcellular location (Human Protein Atlas): Nuclear bodies; Nucleoplasm
Gene Ontology:
Molecular function: protein binding
Genetic constraint (gnomAD): Loss-of-function variants: 27 observed, 31.36 expected, observed/expected ratio (o/e) 0.86, 90% interval 0.63 to 1.19. The upper end of that interval is the gene's LOEUF score, 1.19, which puts it in group 5 of 6, group 1 being the genes least tolerant of losing a copy. Missense variants: 340 observed, 361.35 expected, observed/expected ratio (o/e) 0.94, 90% interval 0.86 to 1.03. Synonymous variants: 132 observed, 147.59 expected, observed/expected ratio (o/e) 0.89, 90% interval 0.78 to 1.03.
Homologues: Orthologues: chimpanzee ANKRD29 (99% identical), macaque ANKRD29 (99% identical), dog ANKRD29 (97% identical), pig ANKRD29 (97% identical), mouse Ankrd29 (96% identical), rat Ankrd29 (96% identical), rabbit ANKRD29 (95% identical), guinea pig ANKRD29 (93% identical), tropical clawed frog ankrd29 (82% identical), zebrafish ankrd29 (72% identical). Paralogues in human: ASB12 (25% identical).
Diseases named in the same sentence as ANKRD29 in open-access papers:
ANKRD29 is named in the same sentence as 5 diseases in open-access papers, as found by Europe PMC text mining. Sharing a sentence is not in itself a finding about the gene and the disease. The quoted sentences say what the papers report.
non-small cell lung carcinoma (2 papers, 2023 to 2025). A group of at least three distinct histological types of lung cancer, including non-small cell squamous cell carcinoma, adenocarcinoma, and large cell carcinoma. "Specifically, ANKRD29 acts as a tumor - suppressor gene, particularly in non - small cell lung cancer (NSCLC) tumorigenesis." (PMID 41367615, 2025). "As a MAPK regulator, the low expression of ANKRD29 may amplify pro-tumor signals in the TME of non-small cell lung cancer (NSCLC)." (PMID 41367615, 2025).
gastric cancer (1 paper, 2025). A primary or metastatic malignant neoplasm involving the stomach. "While EFEMP1 (HR = 1.94, 95% CI 1.27–2.97, p < 0.001), ANKRD29 (HR = 1.77, 95% CI 1.28–2.44, p < 0.001), and STOX2 (HR = 1.50, 95% CI 1.08–2.07, p = 0.014) are all associated with a positive prognostic value for gastric cancer patients." (PMID 41367615, 2025). "Among 20 shared core genes across disease stages, 13 genes (e.g., FCRL3,EFEMP1,ANKRD29,STOX2) were identified as unfavorable prognostic factors for gastric cancer." (PMID 41367615, 2025). "FCRL3, EFEMP1, ANKRD29, and STOX2 may serve as potential biomarkers for monitoring the transition from precancerous lesions to gastric cancer, offering insights into the mechanisms of gastric carcinogenesis and supporting early diagnosis and intervention strategies." (PMID 41367615, 2025).
cancer (2 papers, 2022 to 2023). A tumor composed of atypical neoplastic, often pleomorphic cells that invade other tissues. "In order to evaluate the clinical application potential of ANKRD29, we screened the correlation between ANKRD29 expression and drug sensitivity in pan-cancer from GDSC database." (PMID 37277814, 2023). "Furthermore, ANKRD29 expression was positively related with most immunostimulators, MHC molecules and chemokines expression in LUAD and LUSC from TISIDB website, which suggesting that ANKRD29 expression was involved in cancer cell immune infiltration level." (PMID 37277814, 2023). "Considering the different ANKRD29 expression in immune subtypes of LUAD and LUSC, we analyzed the expression of ANKRD29 in different cell types of NSCLC from TISCH2, a published single-cell RNA sequencing dataset, and found that ANKRD29 predominantly expressed in malignant tumor cells." (PMID 37277814, 2023).
tumor (2 papers, 2023 to 2025). "ANKRD29 functions as a new tumor suppressor in NSCLC tumorigenesis and could be developed as a biomarker for prognostic prediction, immunotherapy response, and drug susceptibility evaluation of NSCLC in the future." (PMID 37277814, 2023). "And we revealed that ANKRD29 could be involved in tumor microenvironment (TME) and served as a promising biomarker of immune checkpoint blockers (ICBs) therapy in NSCLC by integrative bioinformatical analysis and T cell killing assays." (PMID 37277814, 2023). "Reduced ANKRD29 expression significantly enhances NSCLC cell proliferation and migration, while restoring its expression suppresses tumor growth by inhibiting the cell cycle and modulating relevant signaling pathways." (PMID 41367615, 2025). "In conclusion, we identified a new tumor suppressor gene, ANKRD29, which is commonly down-regulated in NSCLC tumor tissues." (PMID 37277814, 2023). "We found that the expression level of ANKRD29 was significantly decreased in tumor tissues compared to normal tissues in TMA." (PMID 37277814, 2023). "As documented previously, tumor microenvironment (TME) played pivotal roles in NSCLC tumorigenesis and drug resistance, we therefore examined whether ANKRD29 was involved in the NSCLC TME regulation." (PMID 37277814, 2023). "In contrast, high expression of ANKRD29 inhibits the proliferation and migration of NSCLC cells, improves anti-tumor immunity by enhancing T cell cytotoxicity, and may counteract the pro-tumor effects of the NF-κB/MAPK axis." (PMID 41367615, 2025).
adenocarcinoma (1 paper, 2018). A common cancer characterized by the presence of malignant glandular cells. "Next the LIMMA analysis of six Y73SV(+) and four Y73SV(−) adenocarcinoma specimens identified one up-regulated gene, MARCH3, and three down-regulated genes, NMNAT2, ANKRD29, and QSER1, in Y73SV(+) specimens." (PMID 30134863, 2018).